CRP (C-reactive protein)
Diseases named in the same sentence as CRP in open-access papers (continued):
Sharing a sentence is not in itself a finding about the gene and the disease.
diabetes (continued). "Among these factors, BMI, ALB, Hb, TG, HDL‐C, HbA1c, CRP >10 mg/L, age, duration of diabetes, Wagner grades 3–5, and using insulin were significantly associated with malnutrition in diabetic patients." (PMID 39364802, 2024). "Patients with diabetes and stress hyperglycemia presented a higher increase in the neutrophil/lymphocyte ratio, serum concentration of C-reactive protein, D-dimer, and ultra-high sensitivity cardiac troponin-l compared to the group without diabetes." (PMID 39079143, 2024). "The nomogram incorporated four clinical features of diabetes mellitus, cryptogenic liver abscess, C-reactive protein level, and splenomegaly, and the Rad-score that was constructed based on seven optimal radiomics features." (PMID 39392039, 2024). "Among these groups, patients with type 2 diabetes mellitus had the highest C-reactive protein concentrations." (PMID 39199338, 2024). "Univariate analysis indicated that age, diabetes status, MIS, age-adjusted CCI, hs-CRP, and albumin were significantly associated with the risk of sarcopenia in both overweight and non-overweight participants." (PMID 38351264, 2024). "This correlation underscores the potential of salivary CRP as a noninvasive tool for tracking diabetes progression and assessing disease severity." (PMID 38741881, 2024). "We performed univariate analysis on these known variables, and only those with a p-value < 0.1 were included in the multivariate model (age, hypertension, diabetes, hyperlipidemia, and CRP were all p < 0.05 in the univariate model)." (PMID 39449074, 2024). "In the final model, 11 variables from the training cohort were identified as independent risk factors for patients with NSCLC: age, KPS score, BMI, diabetes, targeted therapy, Hb, WBC, LDH, CRP, PLR, and LMR." (PMID 39635526, 2024). "In a multivariable model, the MBDA-based CVD risk score added significant information to hypertension, diabetes, tobacco use, history of CVD, age, sex and CRP (HR = 2.27, p = 1.7×10−7)." (PMID 38709770, 2024). "Subgroup analysis by ethnicity revealed that in Western patients, LT was weakly related to ACS presentation, BMI, diabetes, creatinine, hs-CRP, troponin, and coagulation assays (available in the online version)." (PMID 38158199, 2024). "It has been found that ginger consumption shows improvements in diabetes patients by decreasing inflammatory factors like C-reactive protein (CRP), TNFα, and IL6." (PMID 39199328, 2024). "Nomogram integrated five elements of diabetes, renal colic, hemoglobin, CRP and HU value of effusion, then utilized a line segment with a scale to depict the LR model." (PMID 38896174, 2024). "Based on previous studies, there have been similar findings indicating a connection between PEDF and CRP in patients with coronary heart disease, polycystic ovary syndrome, diabetes mellitus, and chronic obstructive pulmonary disease." (PMID 38429803, 2024). "In diabetes, overexpression of pro-inflammatory proteins including C-reactive protein (CRP) and cytokines (IL-1β, IL-6, and TNF-α) contributes to chronic inflammation." (PMID 38291352, 2024). "Participants with lower LDL-C and total cholesterol levels had higher proportion of diabetes, higher CRP levels, and lower serum albumin levels at baseline." (PMID 38626061, 2024). "The findings of the univariate analysis demonstrated that age, sex, race, education level, family income, smoking status, drinking status, diabetes and C-reactive protein were related to migraine." (PMID 38243194, 2024). "Substantial differences were observed for SBP and DBP, diabetes, CRP and smoking across quintiles of FEV1." (PMID 38165527, 2024). "Age > 70 years, smoking history, diabetes history, prolonged use of perioperative antibiotics, and elevated CRP, IL-6, and IGF-1 levels on the 1st day after surgery have an impact on postoperative lung infection in elderly LC patients." (PMID 39495987, 2024).
diabetes (continued). "Measures of high levels of triglycerides, high HbA1c (indicating diabetes) and high CRP recordings are available for mid-40s ages for the 1958 and 1970 cohort and ages in the mid-50s and mid-60s for the 1946 cohort (CRP only available at age 63)." (PMID 39226470, 2024). "In these studies, age, hypertension, body mass index (BMI), diabetes, dyslipidemia, high CRP, smoking, LDL cholesterol, and Lp (a) levels were associated with incident AS." (PMID 39593205, 2024). "Multifactorial logistic regression analysis found that SII (p < 0.001), CRP/HDL-C (p = 0.041), and Diabetes mellitus (p = 0.027) were independent risk factors for frequent PDAP." (PMID 38443857, 2024). "Consistently, in this study, ASCVD patients had an elevated proportion of comorbid diabetes, significantly higher inflammatory markers IL‐6, CRP, and remarkably lower lymphocyte count, lymphocyte percentage and neutralizing antibodies." (PMID 38884329, 2024). "PTSD patients are at higher risk for pre-diabetes, type 2 diabetes, and other comorbidities due to elevated FBS, HbA1C, and CRP." (PMID 38646205, 2024). "Subpopulation analysis of the synergistic effects of C-reactive protein level and periodontitis status on mortality in relation to age, diabetes, hypertension, sex, and deaths related to cardiovascular disease." (PMID 39453923, 2024). "We discovered that the following were independent risk factors for the development of calculous pyonephrosis: hemoglobin, renal colic, CRP, HU value of effusion and diabetes." (PMID 38896174, 2024). "GGO%, CON%, GGO(C/P) and CON(C/P) were correlated with WBC, NLR, LDH, CRP, and comorbidities such as chronic heart disease and diabetes." (PMID 38200566, 2024). "Our results are consistent with the results of previous studies, which declared that CRP is a novel marker for predicting CVDs in patients with diabetes mellitus." (PMID 35997998, 2023). "The most common comorbidities were diabetes mellitus (52%) and hypertension (47.2%).Elevated biomarkers include D-dimer (24.4%), CRP (32.1%), ferritin (26.60%), and others." (PMID 37928498, 2023). "SFACS, BKACS, C-reactive protein, serum albumin, age, diabetes, presence of ischemic heart disease, and critical limb-threatening ischemia were significantly associated with 3-year and 10-year clinical outcomes in the univariate analysis." (PMID 36835836, 2023). "Secondly, univariate regression analysis is used to identify seven independent risk factors related to SSI, including the highest CRP, subcutaneous fat thickness, LPM fat infiltration, diabetes, UTIs, occupation and surgery duration." (PMID 36788621, 2023). "After adjustments for sex, age, hemodialysis vintage, histories of cardiovascular events and diabetes, and C-reactive protein level, a higher ECW/TBW ratio and PEW were independently related to elevated risks of all-cause death." (PMID 37652929, 2023). "BMI, diabetes, smoking history, higher ferritin levels, higher hs-CRP levels, and higher CD3 + T cells before RT were independent risk factors for grade 4 + ARD." (PMID 37308936, 2023). "We included in the model (gender, hypertension, AKI, febrile (yes), CKD, age, SAA, IL-6, CRP, diabetes and proteinuria." (PMID 38203482, 2023). "Patients who needed oxygen supplementation were older; had hypertension, diabetes, or dyspnea; and had a higher level of inflammatory markers, including CRP and procalcitonin." (PMID 36795468, 2023). "The adjusted covariates included age, educational levels, income levels, smoking status, alcohol use, physical activity status, hyper-tension, diabetes mellitus, kidney disease, c-reactive protein, total energy intake (per 1000 kcal) and calcium." (PMID 36771478, 2023). "A total of 1735 participants with diabetes with CRP data (CRP data were only available in the NHANES 2003–2010) were analyzed to determine the relationship between CRP levels and the NLR." (PMID 37775767, 2023).
diabetes (continued). "The objectives of the study were to assess the utility of CEA, CRP, serum albumin level, hemoglobin, and LDH as biomarkers of cancer risk and the biological implications of diabetes on the evolution and prognosis of oncological patients." (PMID 37627906, 2023). "Previous studies documented that, in both diabetes and non-diabetes, markers of inflammation such as C-reactive protein and IL-6 are upregulated after acute hypoglycemia." (PMID 37367911, 2023). "The inverse relationship between fish oil supplementation and CHD risk was significantly mediated by serum CRP in individuals with prediabetes and VLDL-C in patients with diabetes at baseline." (PMID 37513593, 2023). "The adjusted OR was 2.28 (95% CI 1.13‒4.59) even after adjustment for several covariates (age, sex, hypertension, diabetes, CRP, ALT, creatinine, and culprit vessels)." (PMID 37949037, 2023). "Another study observed a significant reduction in C‐reactive protein (CRP) and Interleukin‐6 (IL‐6) levels with vitamin C supplementation in patients with obesity, hypertension, and/or diabetes." (PMID 37823170, 2023). "Based on the studies conducted in patients with hypertension and diabetes, treatment with spironolactone is accompanied by a decrease in the serum levels of many inflammatory markers such as CRP and TNF‐α." (PMID 37933420, 2023). "Notwithstanding, human data on CRP and insulin secretion are limited, as only one cross-sectional study found a link between CRP and impaired insulin secretion in a non-diabetes population." (PMID 37891561, 2023). "It is important that the increase in CRP precedes the appearance of cardiovascular diseases and diabetes." (PMID 37960293, 2023). "In both cohorts, participants with hepatic steatosis appeared to be older, to be more likely to be male, and to have diabetes, hypertension, dyslipidemia, elevated CRP, low eGFR, and higher BMI compared with participants without hepatic steatosis." (PMID 37447388, 2023). "In diabetes mellitus, a high plasma CRP is related to low activity of PON1, independently of pro- and anti-inflammatory adipokines." (PMID 37372026, 2023). "In contrast, some infection markers such as IL-6, and C-reactive protein increase in people who report prolonged sleep, which accelerates the progression of diabetes and its complications." (PMID 36998281, 2023). "Another common inflammatory marker related to diabetes, CRP, has been suggested to be influenced by body fat composition rather than glucose control or insulin sensitivity." (PMID 37520541, 2023). "Subgroup analyses were conducted based on participants with diabetes, baseline blood CRP levels (≥3 mg/L vs. <3 mg/L), and trial duration (≥8 weeks vs. <8 weeks)." (PMID 37970383, 2023). "On theother hand, age of the patients, peak levels of inflammatory markers (CRP andferritin), or presence of co-morbidities, including diabetes and hypertension werenot related to in-hospital mortality in our cohort." (PMID 34082588, 2023). "Understanding variables like CRP, fibrinogen, diabetes, and pre-treatment hearing level that were related to the prognosis of all-frequency SSNHL was done using multivariate logistic regression analysis." (PMID 37634408, 2023). "Positive association maintained after multivariable adjustment with 28% higher odds of diabetes development (OR 1.28; p=0.003; 95% CI 1.09 to 1.50) per one-log increase of baseline hs-CRP." (PMID 37775289, 2023). "Our results show that diabetes increases the level of inflammation markers CRP by 48% in the DM group compared to controls." (PMID 37051364, 2023). "Other characteristics, including age, sex, albumin level, C-reactive protein level, steroids, diabetes mellitus, purpose of TIVAP implantation, primary site of cancer, catheter length, and location of catheter tip, did not demonstrate significant differences." (PMID 37902854, 2023).
diabetes (continued). "Diabetes mellitus, increased levels of CRP, and ferritin were identified as the most significant predictors of poor outcomes in contrast to increased levels of IL-6." (PMID 38034537, 2023). "The Mitchelstown cohort of the Cork and Kerry Diabetes and Health Diseases Study in Ireland reported that levels of inflammatory biomarkers (i.e., CRP, IL-6 and TNF-α) were lower in individuals with higher HEI-2015 scores." (PMID 37347305, 2023). "Age, vascular access, serum albumin, phosphate, CRP, diabetes, congestive heart failure, and malignancy were independent predictors of all-cause mortality in intention-to-treat analyses (model chi-squared: 250, P < 0.001)." (PMID 38106580, 2023). "As such, people with high CRP (>3 mg/L) had comparable vitamin C requirements to people with diabetes; thus, CRP appears to be a suitable surrogate biomarker for determining vitamin C requirements." (PMID 37891943, 2023). "The serum of ALT, AST, AST/ALT ratio, bilirubin, GGT and CRP, which are the most common markers of liver injury, were all higher in pre-diabetes compared to normal control subjects." (PMID 36817440, 2023). "Older age, diabetes, lower acute CRP, higher bilirubin, and lower use of therapeutic anticoagulation were associated with brain MRI abnormalities among patients (appendix pp 34–35)." (PMID 37748493, 2023). "The scoring equation was established as follows: logit(p) = -5.544 + 0.106* BMI+1.228*diabetes + 1.136*smoking history + 1.204*ferritin + 0.682*hs-CRP + 0.729*CD3 + T cells." (PMID 37308936, 2023). "C-reactive protein levels are more than three times higher in patients with diabetes and coronary artery disease than in those with diabetes alone, reflecting some extent of myocardial damage and predicting the tendency to complicate infection." (PMID 36871006, 2023). "Body mass index (BMI), heart rate, diabetes, WBC and CRP were possible risk factors for 30-day mortality in AAA patients after EVAR." (PMID 36860689, 2023). "The multivariate linear regression analysis revealed independent positive associations of ECW/TBW ratio with male sex (β = 0.189), age (β = 0.215), history of diabetes (β = 0.142), Log CRP (β = 0.133), CTR (β = 0.213), and simple PEW score (β = 0.256)." (PMID 37652929, 2023). "For every one-log baseline hs-CRP increment, there was 75% increase in odds of diabetes cases (crude OR 1.75; p<0.001; 95% CI 1.53 to 1.99)." (PMID 37775289, 2023). "After controlling for confounding factors such as age, diabetes, gender, drinking, BMI, smoking, hypertension, and hs-CRP, this connection remained statistically significant (HR=1.24, 95% CI: 1.01-1.52)." (PMID 38288470, 2023). "Our meta-analyses indicate that anti-inflammatory therapies targeting the pathogenic processes of diabetes can significantly reduce the level of FPG, HbA1c, and CRP in patients with T2DM." (PMID 36936906, 2023). "The associations between higher AlkP levels and mortality were attenuated but not eliminated even after adjusting for multiple confounders including BMI, smoking status, diabetes, liver enzymes, C-reactive protein, vitamin D and so on." (PMID 37867513, 2023). "The most common of these include old age, comorbidities (e.g., chronic heart, kidney, and lung diseases; diabetes; hypertension; and obesity), lymphocytopenia, and elevated levels of C-reactive protein (CRP) and D-dimer." (PMID 37109161, 2023). "Increased inflammation as seen by IL - 6 and CRP levels were observed in co-morbidity suggesting that diabetes and HIV co-morbidity worsen the inflammation observed in either disease entity." (PMID 37545969, 2023). "Models 1–3 reveal significant effects of the wealth/CRP groups for incident diabetes/high blood glucose, CHD and stroke." (PMID 37808231, 2023). "The associations of diet with serum levels of advanced glycation end products (AGEs) and high-sensitivity C-reactive protein (hs-CRP) have been examined in patients with type 2 diabetes mellitus (T2DM)." (PMID 37496018, 2023).
diabetes (continued). "There was a more than threefold increase of overall age-standardised cumulative diabetes incidence in the highest hs-CRP tertile 3 (6.3%) when compared with the reference tertile 1 (2.0%)." (PMID 37775289, 2023). "Diabetes mellitus as well as increased levels of CRP and ferritin were found to be the strongest predictors for a poor outcome, and this was not the case for increased levels of IL-6 as was mentioned before." (PMID 38034537, 2023). "In the final joint model, variables noted to significantly increase CVM risk included 10-year age increase, history of diabetes or CVD, 5 g/L serum albumin decrease, and doubling CRP levels." (PMID 37289366, 2023). "Copeptin maintained its predictive value for the composite outcome after adjustment for each of the following factors: diabetes medication, CRP, NT-proBNP, and glomerular filtration rate." (PMID 36676179, 2023). "Studies have shown a significant association between elevated C-reactive protein (CRP), a pro-inflammatory cytokine, and diabetes risk as well as related complications." (PMID 37836510, 2023). "Further, model 1 adjusted the risk factors, including age, educational levels, income levels, smoking status, alcohol use, physical activity status, hypertension, diabetes mellitus, kidney disease, c-reactive protein, and total energy intake (per 1000 kcal)." (PMID 36771478, 2023). "HbA1c and CRP levels, as well as the incidence of diabetes, were higher in Black and Asian individuals than in White individuals, even at a younger age." (PMID 36895058, 2023). "In our data, the CFS was significantly associated with the markers of nutrition (BMI and serum albumin), the marker of inflammation (CRP) and comorbidity of diabetes and cardiovascular diseases, which were the etiologic factors of PEW." (PMID 37696942, 2023). "Increased levels of CRP and IL-6 have previously been associated with an elevated risk of CVD and diabetes." (PMID 37388641, 2023). "Nevertheless, one study reported that 1000 mg of vitamin C supplementation for 8 weeks significantly reduced CRP and IL‐6 levels in participants with obesity, hypertension, and/or diabetes." (PMID 37823170, 2023). "Age, sex, hypertension, diabetes, uric acid, etiological classification of acute ischemic stroke, platelet count, and hs-CRP were considered independent variables." (PMID 37353783, 2023). "There were no statistically relevant links between blood-Cd quartile levels and variables such as sex, age, type 2 diabetes mellitus, fasting lipid profile, CRP and homocysteine values." (PMID 36986164, 2023). "As univariate logistic regression analysis showed, age, duration of diabetes, history of hypertension, SBP, DBP, ALT, urea, Cr, eGFR, HDL-C, CRP, RC, NLR, MLR, and PHR were independently associated with PAD occurrence in T2DM patients (P < 0.05)." (PMID 36875452, 2023). "Participants with higher CumTyG and CumBP values at baseline had higher mean BMI, heart rate, and hs-CRP values; higher prevalences of hypertension and diabetes; and were more likely to be taking antihypertensive, antidiabetic, and lipid-lowering medications." (PMID 38017521, 2023). "Individuals exposed to at least one MetS component had higher BMI, glycated hemoglobin, systolic and diastolic BP, blood chemistry parameters, and CRP than unexposed; they also had more prevalent diabetes and hypertension than the comparison group." (PMID 37038173, 2023). "In the multifactorial regression analysis, serum TB remained an influential risk factor for in-hospital MACE after adjusting for several covariates including age, sex, hypertension, diabetes, CRP, culprit vessels, ALT, and Cr." (PMID 37949037, 2023). "Another meta-analysis encompassing 14 RCTs among individuals with diabetes corroborated the favorable effects of aerobic exercise on the levels of the inflammatory biomarkers CRP and TNF-α." (PMID 37986064, 2023).